ATOH1 (atonal bHLH transcription factor 1)
Diseases named in the same sentence as ATOH1 in open-access papers (continued):
Sharing a sentence is not in itself a finding about the gene and the disease.
rectal tumors (1 paper, 2021). "Aiming to explore the clinical significance of Notch signaling in RC, the possible relation between HES1 and ATOH1 expression levels and various clinicopathological characteristics of rectal tumors were studied to evaluate their prognostic potential." (PMID 34582650, 2021). "ATOH1 mRNA expression was significantly downregulated in rectal tumor tissues compared to normal tissues, with very low levels of ATOH1 expression noted among most of malignant tissues." (PMID 34582650, 2021). "Relative quantitative expression of LGR5, HES1 and ATOH1 in rectal tumor tissues compared to paired non-tumor adjacent tissues revealed significant overexpression of LGR5 and HES1 (p <0.001)." (PMID 34582650, 2021).
respiratory depression (1 paper, 2018). A decrease in ventilation secondary to impaired signals from the central nervous system. "There is ample evidence that NTS neurons directly project to the PBC and our results suggest that the Atoh1-lineage PBC neurons are necessary to prevent respiratory depression in response to hypoxia." (PMID 29972353, 2018). "Atoh1::En1-CKO mice display irregular breathing rhythms, sighs, and apneas, as well as respiratory depression in response to hypoxia and attenuated respiratory response to hypercapnia." (PMID 29972353, 2018).
secondary hypertension (1 paper, 2023). High blood pressure caused by an underlying medical condition. "Rare variation of the SSTR2, ATOH1, and PKD1 genes were associated with secondary hypertension." (PMID 37059828, 2023).
sensorineural deafness (1 paper, 2023). "Thus, the proper duration of Atoh1 expression should be considered when designing future gene therapy strategies for sensorineural deafness." (PMID 37930405, 2023).
tumor (84 papers, 2009 to 2025). "In SCLC, ATOH1 is associated with tumor-initiating capacity and NE differentiation, initially identified in SCLC cell line-derived xenografts (CDX) and promoting tumor cell survival and metastasis." (PMID 41220942, 2025). "miR-375 is the predominant species involved and is strongly associated with the tumor-suppressor gene ATOH1, suggesting a role in tumor differentiation and progression." (PMID 41515546, 2025). "It is also possible that another cell type targeted by the other two Cre transgenes (Netstin and Atoh1) supports tumor growth when Pten loss is heterozygous." (PMID 40766638, 2025). "Increased tumor predisposition in mice defective in the secretory cell lineage differentiation transcription factor atonal homolog 1 (Atoh1)." (PMID 33557139, 2021). "Loss of ATOH1 promotes tumor formation and progression, and mutations in the ATOH1 locus are found with relatively high frequency." (PMID 19243219, 2009). "If loss of ATOH1 were indeed an initiating event in tumor formation, we reasoned that the effects of Atoh1 function would have to be detectable in preneoplastic tissue as this is where oncogenesis begins." (PMID 19243219, 2009). "Given the high deletion and methylation rate of ATOH1 in human tumor samples, loss of ATOH1 function is likely to be an early event in these tumors." (PMID 19243219, 2009). "We assessed the tumor susceptibility of mice with an intestine-specific deletion of Atoh1 (Atoh1Δintestine) in two different established mouse models of CRC." (PMID 19243219, 2009). "If the anti-oncogenic function of Drosophila ato is conserved in its mammalian counterparts, one would predict that the loss and gain of function of ATOH1 would enhance and suppress tumor formation, respectively, in MCC and CRC models." (PMID 19243219, 2009). "In summary, thus far, loss-of-function analysis of Atoh1 in two mouse models of colon tumorigenesis supports a role for Atoh1 as a key switch in tumor formation and progression." (PMID 19243219, 2009). "ATOH1 is associated with chemoresistance and is essential for tumor cell survival." (PMID 40305287, 2025). "In MCC tumors, high ATOH1 expression assessed by IHC correlates with tumor relapse, which may position ATOH1 as a marker with both diagnostic and prognostic relevance." (PMID 38398178, 2024). "Furthermore, the loss of Atoh1 in pit cells shaped cellular interactions and the tumor microenvironment." (PMID 37824217, 2023). "If MCV induces cell proliferation of another skin lineage, and Atoh1 expression is activated either by the virus itself or by complementing mutations, the resulting tumor cells would express several Merkel cell markers and would appear to have arisen from the Merkel cell lineage." (PMID 26544690, 2015). "Thus, the role of Atoh1 in tumor formation is likely linked to its function as a master regulator of differentiation." (PMID 19243219, 2009). "In a more direct approach to investigate the role of ATOH1 in metastasis, we performed intracardiac injection of tumor cells, reasoning that liver metastasis would occur faster, allowing less time for outgrowth of cells with high or re-expressed ATOH1." (PMID 40305287, 2025). "Significantly delayed s.c. tumor growth was observed in mice bearing DOX-induced ATOH1 KD tumors compared to DOX-induced ShRen controls or uninduced tumors." (PMID 40305287, 2025). "We show that, in SCLC cell lines and/or CDX models, ATOH1 regulates neurogenesis, maintains cell survival in vitro, and promotes tumor growth and liver metastasis in vivo." (PMID 40305287, 2025). "As with NEUROD1 and ASCL1 in their respective subtypes, ATOH1 supports cell viability in ATOH1 subtype tumor cells." (PMID 40305287, 2025). "These direct targets comprise the first SCLC-based ATOH1 gene signature consistently observed in CDXs, PDXs, and tumor biopsies, indicative of a conserved transcriptional role for ATOH1 in SCLC." (PMID 40305287, 2025).
tumor (continued). "We combined this approach with positive selection of tumor cells with ATOH1 KD (GFP+ proxy) that remained viable." (PMID 40305287, 2025). "Building upon knowledge of inter- and intra-tumoral heterogeneity, we characterized the ATOH1 subtype, defining its prevalence and demonstrating pro-tumor functions of growth and metastasis." (PMID 40305287, 2025). "We previously reported an additional subtype based on expression of the neurogenic TF ATOH1 within our SCLC circulating tumor cell-derived explant (CDX) model biobank." (PMID 40305287, 2025). "ATOH1 has been considered as a tumor-suppressive gene silenced in gastrointestinal tumors in which it was often expressed at a high level." (PMID 39950044, 2025). "Comparison of TcPP; Atoh1fl/+ and TcPP; Atoh1fl/fl mice subjected to tamoxifen induction revealed that Atoh1 knockout increased tumor burden." (PMID 37824217, 2023). "We used stomach‐specific Atoh1 mouse models to determine the functions of ATOH1 in the GAC and found that Atoh1 deficiency induced CSC‐like properties and increased the tumor burden." (PMID 37824217, 2023). "GAS1 reduction reversed the inhibitory effects of ATOH1 overexpression on heterologous tumor growth and tumor initiation." (PMID 37824217, 2023). "We observed strong focal staining of YAP1 and WWTR1 in a subpopulation of cells within a tumor section that was otherwise positive for H&E and ATOH1 (red arrows)." (PMID 36719743, 2023). "Consistent with previous reports, all H&E-positive tumor sections stained for ATOH1 (7 of 7) and most for KRT20 (5 of 7)." (PMID 36719743, 2023). "We found that ATOH1 mRNA expression levels were positively correlated with GAS1 in 48 primary tumor samples (P < 0.001)." (PMID 37824217, 2023). "To further analyze the potential biological mechanisms through which ATOH1 affects the curative efficacy of tumor ICI treatment, we performed a GSEA on the TCGA-COAD cohort." (PMID 35836254, 2022). "It has been demonstrated that ATOH1 has a tumor-suppressing function and that it is also decreased in CRC." (PMID 36344988, 2022). "MCC tumor cells also express signature genes detected in skin-resident, postmitotic Merkel cells, including atonal bHLH transcription factor 1 (ATOH1), which is required for Merkel cell development from epidermal progenitors." (PMID 35143422, 2022). "Expression study of LGR5, HES1 and ATOH1 were performed by quantitative PCR (QPCR) based on comparative Cq method after normalization to adjacent non tumor tissues and ACTB as a reference gene." (PMID 34582650, 2021). "Similar to normal Merkel cells, MCC tumor cells express ATOH1, the transcription factor driving Merkel cell differentiation." (PMID 35062263, 2021). "Regarding the association of clinical findings with ATOH1 expression, the present work didn`t find significant correlation between ATOH1 mRNA levels and various tumor criteria." (PMID 34582650, 2021). "In contrast, M-Smo tumors, generated by initiating SmoM2 expression in Atoh1-expressing committed neural progenitors, contained more differentiating tumor cells at P15." (PMID 34021242, 2021). "The influence of miRNA in MCC carcinogenesis was integrated either by downregulation, overexpression or correlation to ATOH1 tumor suppression gene." (PMID 34946878, 2021). "The study detected overexpression of LGR5 and HES1 and down-regulation of ATOH1 in human RC tissues compared to non- tumor tissues." (PMID 34582650, 2021). "Conversely, ATOH1 was significantly down regulated in tumor tissues relative to non- tumor adjacent tissues (p= 0.05)." (PMID 34582650, 2021). "Of note, although CDX1 and CDX2 were found to be both inactivated and underexpressed, several TFs such as KLF5 or ATOH1 with established tumor suppressor roles in colorectal cancer were only found inactivated via SCIRA." (PMID 33083012, 2020).
tumor (continued). "Although Atoh-1 has been shown to function as a tumor suppressor, patients with mucinous colorectal tumors exhibit high levels of Atoh-1 expression and retain prominent secretory cell components possibly due to the absence or inactivation of Notch-1 signaling." (PMID 30323897, 2018). "Biochemical experiments showed that the tumor stem cells of the mice contain a modified version of Atoh1 where a phosphate molecule is bound to a particular region of the protein." (PMID 29168692, 2017). "Although the neuronal lineage marker Atoh1 was used to sort for CGNPs, the resulting tumor cells had lost Atoh1 expression and instead displayed increased expression of Prominin1 and other stem cell factors." (PMID 28333115, 2017). "Both tumor types exhibited classic histology, and similar expression patterns for expected Shh-MB neural markers (Atoh1, TUBB3 and GFAP) and Hh target genes (Gli1, Mycn and Ccnd1)." (PMID 27823583, 2016). "Pairwise unsupervised clustering using a subset of the most variant genes (top 5%, n=1,076) showed that both types of CRISPR-Ptch1 tumours are most similar to germline Ptch1+/− and Atoh1-CreER;Ptch1fl/fl16 MB models." (PMID 26067104, 2015). "In contrast with its effect on differentiation, ATOH1 can also promote the proliferation of progenitor cells and tumor formation." (PMID 25950549, 2015). "BMPs cause rapid turnover of the basic-helix-loop-helix transcription factor Atonal (Atoh1, Math1 in mice) which is required for cerebellum development and tumor formation." (PMID 23527084, 2013). "The RTK and JNK signaling pathways, which are essential for Atoh1's tumor suppressor activity, have been suggested as context-dependent oncogenes or tumor suppressors." (PMID 19243219, 2009). "Loss-of-function mutations in ATOH1 prevent JNK-mediated apoptosis and p21-mediated cell cycle arrest, leading to enhanced tumor progression." (PMID 19243219, 2009). "Combined with evidence that atonal's mammalian homolog, ATOH1, is a tumor suppressor gene, our data support a critical, evolutionarily conserved, function for ato in oncogenesis." (PMID 19243220, 2009). "Data from mouse models indicate an involvement of JNK-mediated regulation of cell proliferation for the tumor suppressor effect of Atoh1." (PMID 19243219, 2009). "Compared to other molecular subtype CDXs (14 ASCL1 CDXs, 4 NEUROD1 CDXs, and 4 ATOH1 CDXs), ATOH1 CDXs were the most aggressive, taking only 61 days to reach the target tumor volume of 800–1,000 mm2 compared to ASCL1 (75 days, p = 0.0128) and NEUROD1 (95 days, p < 0.0001)." (PMID 40305287, 2025). "ATOH1 supports aggressive tumor growth, including liver metastasis." (PMID 40305287, 2025). "In vivo, ATOH1 depletion slows tumor growth and suppresses liver metastasis." (PMID 40305287, 2025). "When ATOH1 function is disrupted, tumor cells may lose their Merkel cell identity and acquire stem-like characteristics, leading to malignancy." (PMID 40589575, 2025). "We next asked whether the role of ATOH1 in maintaining cell survival ex vivo translated to impact on tumor growth in vivo." (PMID 40305287, 2025). "Additionally, knocking down Ndrg1 in BLM tumor organoids reduced secretory progenitor marker gene expression (Sox4, Atoh1, Dll1, Notch1), but increased enterocyte marker gene expression (Cdhr2, Aqp8)." (PMID 38893159, 2024). "Conversely, ATOH1 knockdown reduced xenograft tumor sensitivity to 5‐FU." (PMID 37824217, 2023). "ATOH1 is frequently downregulated and plays a tumor suppressive role in CRC." (PMID 35619909, 2022). "In addition, they have shown that treatment of the tumor-bearing Atoh1-SmoM2 mice with a CSF1R inhibitor prolonged survival." (PMID 36291792, 2022). "ATOH1 plays a key role in SHH-MB by mediating the transit proliferation of granule cell precursors and suppressing differentiation in response to SHH, which is secreted by Purkinje cells, MB cells, and tumor-associated astrocytes." (PMID 36291792, 2022).
tumor (continued). "It was suggested that tumor suppressive function of ATOH1 is mediated by its effects on CSCs." (PMID 34582650, 2021). "Subsequently, using a SHH‐MB genetic mouse model, Atoh1‐Cre; SmoM2+/−, we demonstrated that ablation of Rack1 could significantly inhibit the growth of tumor cells with a dramatically extended lifespan in rescue mice." (PMID 34480519, 2021). "Novel therapies using antisense oligonucleotides or miRNAs that can regulate Atonal homolog 1 (ATOH1) expression, a tumor suppressor gene, could bring new clinical approaches in this disease." (PMID 32185171, 2020). "Here, loss of Atoh1 prevented JNK-mediated apoptosis, leading to tumor progression." (PMID 28779171, 2017). "Heterozygosity of Atoh1 reduced tumor occurrence and prolonged survival." (PMID 29168692, 2017). "In addition, we examined the status of the ATOH1 locus in primary tumor samples from human MCC and CRC patients." (PMID 19243219, 2009). "The activation and co-option of RTK and JNK signaling by Ato/ATOH1 in this context suggests that the status of differentiation of the tumor-initiating cell may be the key determinant of the specific role of various signaling pathways in cancer." (PMID 19243219, 2009). "Our data support an evolutionarily conserved tumor suppressor role for ATOH1 in CRC and MCC." (PMID 19243219, 2009). "To test this possibility in vivo in primary human tumors, we began by asking whether the expression of ATOH1 is down-regulated in primary tumor samples from 42 CRC and four MCC patients." (PMID 19243219, 2009). "Overall, these data indicate that reduced ATOH1 expression promotes tumor growth delay in vivo, where impact may have been attenuated by outgrowth of ATOH1+ cells, which are potentially untransduced wild-type cells or cells that escaped inducible KD, as reported in other settings." (PMID 40305287, 2025). "Therefore, Dll4/Notch inhibition may also negatively affect the tumor stem cell populations through Atoh1 derepression-mediated upregulation of the CDK inhibitors Cdkn1b and Cdkn1c." (PMID 28086833, 2017). "At tumor resection, mice bearing DOX-induced ATOH1 KD tumors showed a 75% reduction in ATOH1 protein expression, and both DOX-induced controls and KD tumors had high expression of GFP." (PMID 40305287, 2025). "Within the Pax6+ clusters 0–9, based on marker gene expression and cell cycle phase, clusters 3, 4, 8 were proliferative (Ki67+) and enriched for the GCP markers Gli1, Atoh1 and Barhl1, indicating highly proliferative GCP-like tumor cells." (PMID 40766638, 2025). "Atonal Homolog 1 (ATOH1) and SOX2 are PTFs that play vital roles in Merkel cell differentiation, and tumor-suppressing pathways." (PMID 40589575, 2025). "In summary, we validate the ATOH1 SCLC subtype, where ATOH1 suppresses cell death and promotes tumor growth and metastasis." (PMID 40305287, 2025). "Strikingly, expression of ATOH1 and KRT20 varied in intensity and positivity within individual tumor sections, indicating the potential for heterogenous subpopulations." (PMID 36719743, 2023). "To interpret the observed growth delay, we examined persistence of ATOH1 KD throughout the experiment by performing IHC for ATOH1 and GFP in resected s.c. tumors (mean tumor volume and time from implant: 603 ± 54 mm3, 44 ± 5 days ShRen +DOX; 552 ± 48 mm3, 70 ± 13 days ShATOH1 +DOX)." (PMID 40305287, 2025). "However, GFP expression was ∼10% lower in DOX-induced ATOH1 KD tumors (p = 0.008) and expression of GFP and ATOH1 was heterogeneous in DOX-induced ATOH1 KD tumors, with most tumor presenting with some GFP−, ATOH1+ regions." (PMID 40305287, 2025). "Interestingly, we showed that knocking down Cdx2 significantly reduced the expression of differentiated lineages-related genes such as Muc2, Atoh1, and Guca2a in BRAF mutant tumor-derived organoids." (PMID 38893159, 2024). "ATOH1 protein levels were significantly lower in 147 primary tumor samples than in adjacent noncancerous tissues from FJMUUH patients." (PMID 37824217, 2023).